AKAP12 (A-kinase anchoring protein 12)
Diseases named in the same sentence as AKAP12 in open-access papers (continued):
Sharing a sentence is not in itself a finding about the gene and the disease.
tumor (continued). "Most tumor types in the present study were correlated with the low expression levels of AKAP12 and matched high methylation levels of AKAP12 promoters relative to normal tissues, in the support of both previous studies and the potential role of AKAP12 as a biomarker." (PMID 36110213, 2022). "Our data indicate that, compared to WT C57BL/6 controls, Akap12-null mice suffer from an increased burden of macrometastases in multiple organs, derived from spontaneous metastasis of s.c. tumors and from experimental metastases induced by i.v. tumor injections." (PMID 29050279, 2017). "Based on the ability of SSeCKS/AKAP12 to attenuate Src-mediated metastatic signaling at the tumor cell level, and based on roles for TME-expressed SFK in regulating metastasis (above), we addressed whether SSeCKS also plays a role in the TME to regulate metastatic potential." (PMID 29050279, 2017). "Therefore, we propose that AKAP12 functions as a tumor suppressor of this solid cancer." (PMID 21918680, 2011). "The heatmap demonstrated SERPINE1 was up-regulated in tumor tissues, while the rest four genes (ZFP36, DUSP1, CAV1, and AKAP12) were down-regulated as compared to the normal group." (PMID 39165353, 2024). "SETD1A knockdown changed the landscape of SEs, resulting in activation of the transcription of SE-driven tumor suppressors, such as ST3GAL4, AKAP12, PTPN1, AQP9, and ANKRD11." (PMID 37581938, 2023). "While the Tumor_2 had relative mild cancer hallmark signatures but expressed genes associated with tumor survival signal and drug resistance (IL32, TOX2, AIF1, AKAP12, CD38 etc.), and eventually became the main tumor subtype post-treatment." (PMID 36417130, 2023). "Consistency between the proteomics data and tumor gene expression was also reported for the upregulation of FN1 and the downregulation of CALR and AKAP12 in the HR-NB patients compared to the LR-NB cases." (PMID 37947594, 2023). "In contrast to LOX and AKAP12, we found that MAFF transcriptionally regulates a different set of target genes to promote tumor invasion and metastasis." (PMID 34262028, 2021). "We found that, in addition to interacting with CD2, CD58 was co-expressed and physically interacted with HOXB family genes (HOXB2, HOXB3, and HOXB5), AKAP12, CLIC1, CPNE3, etc., which were reported to be involved in tumor initiation and progression." (PMID 34193136, 2021). "AKAP12 and DCBLD2 were frequently detected at lower levels in tumor (T) than normal matched tissues (N)." (PMID 24133572, 2013). "Taken together, this substantial evidence strongly confirms that these HMDRGs (ZFP36, SERPINE1, AKAP12, CAV1, and DUSP1) are strongly involved in hypoxia, mitochondrial dysfunction, and tumor immunity, in turn contributing to the modulation of GC pathogenesis and prognosis." (PMID 39165353, 2024). "The expression of PER1, AKAP12 and MMP17 was located in the cytoplasm of tumor cells." (PMID 37434173, 2023). "AKAP12 exerts a tumor-suppressive function through the negative modulation of angiogenesis, cell proliferation and migration by preventing PKC activation." (PMID 37947594, 2023). "Two genes, ANXA1 and AKAP12, were enriched in both mouse and human TROP2-producing tumor cells." (PMID 36077674, 2022). "We further verified the expression levels of ADAMTS9, ENTPD1, FRMD3, PRR15, AKAP12 in THCA, and the results of GEPIA database showed that ENTPD1, FRMD3, PRR15 were obviously increased in tumor tissues (n=512) compared with normal tissues (n=337), and the difference was statistically significant." (PMID 35756646, 2022). "Gene expression analysis showed that several genes involved in tumor development and metastasis (EGR1, COX2, MALAT1, AKAP12, ADM) were similarly induced in CSC and cisplatin-resistant H460 cells, in agreement with a close similarity between these two cell populations." (PMID 24961511, 2014).
tumor (continued). "AKAP12, DCBLD2, NT5E and SPON1 are particularly represented in the signatures and selected for validation in vivo on two independent patients cohorts comprising 140 tumor tissues and 60 matched normal tissues." (PMID 24133572, 2013). "Akap12's rapid expression kinetics in SMC following retinoid stimulation, its dependence on de novo mRNA synthesis, and its independence for de novo protein synthesis indicate that this tumor suppressor is a retinoid-induced, immediate-early gene." (PMID 21483686, 2011). "Results suggest that AKAP12, APOL3, CXCL13, CXCL9, GBP4, and LRIG1 may act as tumor suppressors." (PMID 35677536, 2022). "Considering the difference in molecular detail between tumorigenesis and chemosensitivity, our finding suggested that AKAP12 was not an oncogene but could act as a resistance-related gene in tumor progression." (PMID 36110213, 2022). "However, as a well-known tumor suppressor, the immune implication of AKAP12 in STAD has not been explored." (PMID 36148016, 2022). "SSeCKS/Gravin/AKAP12 is among a growing list of so-called metastasis suppressors, defined as gene products that can experimentally suppress specific parameters of metastatic progression while having limited or no role in primary tumor formation." (PMID 29050279, 2017). "Moreover, inhibitor of growth, i.e. Tgfb1, Gadd45b, Igfbp6, A-kinase-anchoring protein (Akap12) and protein tyrosine phosphatase, non-receptor type substrate 1 were highly significantly repressed, from which their important role in tumor progression can be inferred." (PMID 29254206, 2017).
cancer (51 papers, 2010 to 2025). A tumor composed of atypical neoplastic, often pleomorphic cells that invade other tissues. "In many cancers, AKAP12 downregulation is usually associated with malignant tumor progression and metastasis." (PMID 40226362, 2025). "For the immunologic significance, AKAP12 was positively related to the abundance of pro-tumor cancer-associated fibroblasts (CAFs) in various types of cancer." (PMID 36110213, 2022). "In our study, AKAP12 was downregulated in almost all cancers but was negatively associated with anti-VEGF therapy sensitivity in OV, GBM, CRC, and LUSC." (PMID 36110213, 2022). "Evidence is accumulating that AKAP12 expression is downregulated in many cancer types, either associated with gene deletion or epigenetic downregulation due to promoter hypermethylation or changes in chromatinization." (PMID 22811901, 2012). "Dysplastic foci were observed less frequently but were associated with the loss of E-cadherin staining and the loss of basal cell markers, suggesting that the loss of AKAP12 causes a cancer-prone condition." (PMID 22811901, 2012). "Indeed, Crkl, which seems to drive the activation of p110β in PTEN-deficient cancer cells, was significantly increased in PC tumors from Pten/Rb-null vs. Akap12/Rb-null mice." (PMID 37292818, 2023). "AKAP12 deletion is associated with increased cancer susceptibility." (PMID 36591507, 2022). "The low methylation status of AKAP12 may also underlie the upregulation of AKAP12 in cancers with anti-VEGF therapy resistance, and predicts worse prognoses." (PMID 36110213, 2022). "To examine whether there is an association between certain genetic alterations of AKAP12 and clinical outcomes of patients, we systematically analyzed and correlated these with diverse cancer types." (PMID 36110213, 2022). "Conclusively, AKAP12 may play an important role in cell cycle regulation and may thus represent a potential target for the treatment of cancer and other proliferation-associated diseases." (PMID 26202611, 2015). "The TIMER database showed that AKAP12 was differentially expressed in the Cancer Genome Atlas (TCGA) pan-cancer dataset." (PMID 40226362, 2025). "Our study showed that AKAP12 was downregulated in cancer tissues, as compared to control (p < 0.05), which further confirmed the conclusion of the current analysis." (PMID 37795791, 2023). "Previous literature convincingly demonstrated that elevated AKAP12 expression in LUAD facilitated cancer cell proliferation, migration, and invasion and suppresses cell apoptosis, a similar study corroborating our conclusion." (PMID 36110213, 2022). "In the present study, based on bioinformatics technology, increased expression of AKAP12 was proved to influence the prognosis of BV-treated cancer patients." (PMID 36110213, 2022). "The present study first systematically analyzed the association of AKAP12 with anti-VEGF inhibitors’ sensitivity, clinical prognosis, DNA methylation, protein phosphorylation, and immune cell infiltration across various cancers via bioinformatic tools." (PMID 36110213, 2022). "Several studies have confirmed that decreased expression of AKAP12 in advanced cancer was attributed to upregulated hypermethylation of the 5′ CpG island within the AKAP12 promoter region." (PMID 36110213, 2022). "Among these proteins, AKAP4 and AKAP9 have been extensively studied as cancer-promoting factors, whereas AKAP12 and recently AKAP13 have been shown to play the opposite role, although their mechanism of action has not been studied in depth." (PMID 36203781, 2022). "In our study, AKAP12 expression was positively connected with macrophage infiltration in several cancer types." (PMID 36110213, 2022). "Based on CCLE database, we found that AKAP12 coexpressed genes were enriched in several immune- and cancer-related pathways, which was further validated by Gene Set Enrichment Analysis (GSEA)." (PMID 36148016, 2022).
cancer (continued). "The correlation between the expression of INSIG1 as well as AKAP12 and their corresponding prognosis in cancer patients receiving BV was analyzed applying the Kaplan–Meier plotter database and two GEO datasets." (PMID 36110213, 2022). "Subsequently, AKAP12 was found to inhibit malignant tumor metastasis and progression, regulate the formation of blood-brain and blood-retinal barriers, and resensitize β2-adrenergic pain receptors." (PMID 36238643, 2022). "We systematically describe the drug sensitivity, prognostic significance, and the genetic alteration states of AKAP12 among different cancer types." (PMID 36110213, 2022). "The inconsistent role of AKAP12 suggested the possibility of usage of AKAP12 inhibitors contributed to the strategies of precision medicine in future medical inventions based on variable cancer types and specific drug resistance." (PMID 36110213, 2022). "On the other hand, augmented expression of AKAP12 in both cisplatin- and paclitaxel-resistant cancer cells indicates a cancer-protective role of AKAP12." (PMID 36110213, 2022). "This comprehensive analysis suggests potential molecule mechanisms of AKAP12 in the pathogenesis and prognosis of multiple cancer types, providing some reference for target therapies." (PMID 36110213, 2022). "Next, we tended to focus on understanding how AKAP12 expression related to the prognosis of patients afflicted with cancer." (PMID 36110213, 2022). "Thereupon, we performed a pan-cancer analysis to explore the detailed roles of AKAP12 across various cancers." (PMID 36110213, 2022). "Downregulation of gravin (AKAP12) was frequently observed in various cancers including prostate, ovarian, and breast cancers, and depletion of gravin promotes progression of these cancers." (PMID 36317124, 2022). "Among them, AKAP4 and AKAP9 have been widely studied as cancer-promoting factors, while AKAP12 have proved to play the opposite role." (PMID 34722307, 2021). "AKAP12 protein belonged to the family of kinase scaffolding protein and participated in signal transduction of cancer." (PMID 34122523, 2021). "AKAP12 (A kinase anchor protein 12), a family member of A-kinase scaffold proteins played contributory role in cancer suppression." (PMID 29614790, 2018). "Cisplatin, paclitaxel, and radiation induce DNA breaks, suggesting a cancer protective role for AKAP12." (PMID 29391485, 2018). "Down-regulation of AKAP12 suppresses cell proliferation, survival, motility, migration, anchorage independent growth, angiogenesis and invasion in several cancers." (PMID 29653561, 2018). "AKAP12 gene is mapped to 6q24-25.2, which is a hotspot for gene deletions during cancer progression." (PMID 26202611, 2015). "Although both AKAP12 and Ezrin seem to inhibit proliferation, as outlined in detail above Ezrin, seems to change its function in cancer." (PMID 26202611, 2015). "The portal also allows quick identification and visualization of all direct interaction partners of AKAP12, which includes other well-known cancer genes such as EGFR and PRKCA." (PMID 25527095, 2015). "Three of these genes, JUN, EGR1, and AKAP12, are involved in the control of cell proliferation and cancer progression." (PMID 24961511, 2014). "Results from those studies would strongly suggest that targeting PKC-regulators such as AKAP12 should have therapeutic benefit for cancer patients." (PMID 22811901, 2012). "In the present study, we examined this question through re-expression of AKAP12 in AKAP12-null cancer cells to determine if this would influence cancer cell growth and metastatic potential." (PMID 21918680, 2011). "In general, and consistent with data in the cancer field, Ki-67 positive cells showed weak AKAP12 staining, especially in 3 week injured vessels where a prominent neointima is manifest." (PMID 21483686, 2011). "In particular, ZNF483 and AKAP12 emerged as the strongest down-regulated circRNAs in cancer." (PMID 37106694, 2023).
cancer (continued). "Our study showed that the dual role of AKAP12 in various cancers and AKAP12 could serve as a biomarker of anti-VEGF resistance in OV, GBM, LUSC, and COAD." (PMID 36110213, 2022). "Considering the negative association with drug sensitivity and predictable capacity for shorter survival, the silencing of AKAP12 in these cancer types might, to some extent, enhance cancer patients’ response to anti-VEGF therapy." (PMID 36110213, 2022). "Also, AKAP12 expression was correlated with higher IC50 values of sunitinib in metastasis pan-cancer." (PMID 36110213, 2022). "Recently, the divergent functions of AKAP12 in cancers have been studied extensively." (PMID 36110213, 2022). "The results indicated that AKAP12 might play a paramount role in the progress of cancer progression." (PMID 36110213, 2022). "Moreover, AKAP12 expression was negatively correlated with cancer sensitivity towards anti-VEGF therapy." (PMID 36110213, 2022). "AKAP12 controls cell signaling pathways and accelerates oncogenic development in cancer." (PMID 36589842, 2022). "Finally, single-cell sequencing data were employed to explore relevant cancer cell states of AKAP12." (PMID 36110213, 2022). "In addition, PPARG2 also showed a positive correlation in mRNA expression with AKAP12 in most cancer and normal tissues or cell lines." (PMID 34023860, 2021). "AKAP12 was regarded to be strictly connected with several human cancers." (PMID 33251130, 2020). "Network-based analysis thus suggests potential importance of AKAP12 in cancer." (PMID 25527095, 2015). "On the other hand, restoration of AKAP12 expression might be beneficial in future treatment of cancer." (PMID 26202611, 2015). "AKAP12 has been mapped to chromosome 6q24–25.2, a cancer deletion hotspot." (PMID 21918680, 2011). "Importantly, AKAP12 was confirmed to be downregulated in lung adenocarcinoma, and its inhibition might block cancer malignant progression." (PMID 40226362, 2025). "Furthermore, lower expression of AKAP12 was detected in nearly all cancer types, and hypermethylation may explain its decreased expression." (PMID 36110213, 2022). "Therefore, our results suggested that AKAP12 might be involved in cancer resistance to anti-VEGF inhibitors, especially for BV." (PMID 36110213, 2022). "However, the role of AKAP12 in pan-cancer remains poorly defined." (PMID 36110213, 2022). "Also, the drug sensitivity analysis revealed a negative association between AKAP12 expression and the sensitivity of certain cancer types towards anti-VEGF inhibitors." (PMID 36110213, 2022). "Thus, whether AKAP12 could promote anti-VEGF therapy resistance via elevating the migratory capacity of cancer cells need to be elucidated." (PMID 36110213, 2022). "On comparison of the expression of PER1, AKAP12, and MMP17 in TCGA with that in the GTEx dataset, the levels of the three genes were higher in normal ovarian tissues than in cancer tissues." (PMID 37434173, 2023). "A literature review indicates that hypermethylation of AKAP12 and accompanied under-expression of the gene has been noted in CRC as well as other human cancers." (PMID 25527095, 2015). "Other identified common up-regulated hub genes such as AKAP12, WFDC2, CALD1, and VSNL1 are related to drug resistance in various cancers although their involvement in oxaliplatin resistance in CRC was not identified and can be reported as protentional biomarkers which merits further exploration." (PMID 37535601, 2023). "Among these, AKAP12 and ZNF483 emerged as the most differentially down-regulated coding circRNAs whereas AFTPH, CHST15 and WDR37 were differentially up-regulated in the pan-cancer RNA-Seq dataset." (PMID 37106694, 2023). "The reduced AKAP12 expression seen in FOLFIRI responders vs. non-responders might be because these cancers do not have cell death inhibited." (PMID 38304289, 2023).
cancer (continued). "Nevertheless, we also identified that AKAP12 indicated better prognoses in KIRC, LAML, and THCA, this might be attributed to the difference in genetic heterogeneity and clinical features of different cancer types and subtypes." (PMID 36110213, 2022). "Unlike AKAP12, Ezrin expression and increased malignancy seem to correlate in various human cancers, including uterine cervical cancer, uveal malignant melanoma, tongue SCC, hepatocellular carcinoma, brain astrocytoma, and atypical endometrial hyperplasia and uterine endometrioid adenocarcinoma." (PMID 26202611, 2015).
bacterial infections (1 paper, 2024). "For example, AKAP12, an A-kinase anchoring protein transcribed in endothelial cells (42, –44), was more abundant in KD and MIS-C as compared to viral and bacterial infections, and selected by each of the 1v1 models designed to differentiate KD and MIS-C from viral and bacterial infections." (PMID 39240972, 2024).
brain disease (1 paper, 2024). "Future research is warranted to explore the therapeutic potential of AKAP12 in sex-related brain diseases." (PMID 39574214, 2024).
neurological diseases (1 paper, 2021).
AKAP12 also shares sentences with these, for which no sentence is quoted: prostatic adenocarcinomas (3 papers); acute lymphoblastic leukemia (2); Barrett esophagus (2); chronic obstructive pulmonary disease (2); diabetes (2); esophageal adenocarcinoma (2); Hypertension (2); Infertility (2); memory impairment (2); prostatic intraepithelial neoplasias (2); serous ovarian carcinomas (2); triple-negative breast carcinoma (2); abdominal aortic aneurysm (1); bladder urothelial carcinoma (1); brain injury (1); Cerebral ischemia (1); cervical squamous cell carcinoma (1); colon adenocarcinoma (1); Crohn disease (1); endocervical adenocarcinoma (1); endometrial cancer (1); endothelial dysfunction (1); esophageal neoplasm (1); female infertility (1); Fibroadenoma (1); fibromyalgia (1); geographic atrophy (1); head and neck squamous cell carcinoma (1); infection (1); liver disease (1).
A further 20 diseases each share a sentence with AKAP12 in 1 paper.